MYCN (MYCN proto-oncogene, bHLH transcription factor)
Diseases named in the same sentence as MYCN in open-access papers (continued):
Sharing a sentence is not in itself a finding about the gene and the disease.
neuroblastoma (continued). "Therefore, to understand how 4h and 4k broadly influence neuroblastoma cell function, we paneled the cellular activity of both compounds against four MYCN single copy lines, SH-EP, SH-SY5Y, SK-N-AS, and SK-N-SH, which each differ in their genetic risk factors." (PMID 40430358, 2025). "Furthermore, c‐MYC also binds the ATP13A3 and ODC1 promoter in neuroblastoma cells, albeit at a different region than MYCN, potentially denoting differences in MYCN and c‐MYC‐mediated regulation of expression." (PMID 39981745, 2025). "For example, transcription factor 4 (TCF4) binds to the AJUBA SEs and promoter to promote epithelial-mesenchymal transition (EMT) and metastasis in hepatocellular carcinoma (HCC), while MYCN invades and binds to enhancers to amplify tumor-specific transcriptional outputs in neuroblastoma." (PMID 41462308, 2025). "MYCN sensitizes neuroblastoma cells to cytotoxic drugs by cooperatively upregulating BAX." (PMID 40365336, 2025). "Similarly, mice implanted with SIMA (with MYCN amplification) cell line–based xenografts also showed excellent outcomes after the completion of a 10-day treatment, but the neuroblastoma eventually relapsed." (PMID 40962798, 2025). "We transiently overexpressed HIF2α in the MYCN-amplified Kelly neuroblastoma cells." (PMID 41118218, 2025). "In summary, these results show that KLHL37 might be a promising therapeutic target for MYCN-amplified neuroblastoma." (PMID 40493396, 2025). "Moreover, Kit gene has been reported to be preferentially expressed in MYCN-amplified neuroblastoma." (PMID 41142119, 2025). "Given that MYCN is a key oncogenic driver in high-risk neuroblastoma and governs a broad transcriptional network, we hypothesized that NIPBL may colocalize with MYCN in the neuroblastoma genome." (PMID 40867243, 2025). "Therefore, upregulated glycolysis in MYCN-amplified neuroblastoma represents a compelling target for this treatment strategy." (PMID 41291487, 2025). "In SMG samples from 2-week-old Th-MYCN+/− mice, most MYCN+ neuroblastoma cells expressed Ube2c." (PMID 40580553, 2025). "These transcriptional changes were paralleled by the induction of neuronal markers and morphological signs of neuronal differentiation, indicating that NIPBL is essential for maintaining the undifferentiated, stem-like state of MYCN-amplified neuroblastoma cells." (PMID 40867243, 2025). "Here, we demonstrate that targeting highly amplified regions within the genome, such as MYCN in neuroblastoma cells, with the RuvC mutant SpyCas9D10A nickase affords an opportunity to exploit genomic vulnerabilities to induce cell death in a gene amplification-dependent manner." (PMID 40456709, 2025). "To understand the molecular process of the regulatory effect of KLHL37 on MYCN-amplified neuroblastoma, we wonder whether KLHL37 could directly regulate N-Myc protein." (PMID 40493396, 2025). "Targeting NIPBL may offer a novel strategy to disrupt MYCN-driven transcription and promote tumor cell differentiation in MYCN-amplified neuroblastoma, ultimately improving therapeutic outcomes in this aggressive pediatric cancer." (PMID 40867243, 2025). "In neuroblastoma, the expression levels of MYCN and DKK3 are negatively correlated." (PMID 41244073, 2025). "Given the success of Cas9D10A in the selective depletion of MYCN-amplified neuroblastoma cells, we asked whether our observations would translate to other cancer types exhibiting gene amplification." (PMID 40456709, 2025). "We observed that both ABCA13 and LRP1B are expressed at higher levels in MYCN non-amplified neuroblastoma, a subgroup typically associated with less heterogeneous outcomes." (PMID 40599792, 2025). "This variant was found to be located in open chromatin regions identified in 29 ATAC‐seq and 5 H3K27ac ChIP‐seq experiments in various neuroblastoma cell lines, but also showed the highest enrichment of TF binding sites, including MYCN, LMO1, GATA3, HAND2, ISL1, PHOX2B, and TBX2." (PMID 40525640, 2025).
neuroblastoma (continued). "Here, we demonstrate that PA2G4 is essential for MYCN-driven tumor growth in neuroblastoma in vivo." (PMID 41002386, 2025). "Strengthening diagnostic and therapeutic capabilities in middle-SDI regions is paramount, alongside investments in genetic and molecular research, such as exploring the role of MYCN amplification in neuroblastoma, to support the development of personalized treatment approaches." (PMID 40963964, 2025). "Using non-invasive magnetic resonance imaging (MRI), we have shown the Th-MYCN murine model as a faithful representation of human neuroblastoma with regards to its anatomical and radiological appearance, as well as its high sensitivity to treatment with cyclophosphamide." (PMID 40359728, 2025). "In line with our previous results and similar to ATP13A3 silencing, AMXT 1501 effectively blocks putrescine and spermidine uptake and prevents the DFMO‐induced compensatory increase in polyamine uptake in both MYCN‐amplified and non‐MYCN amplified neuroblastoma cells." (PMID 39981745, 2025). "Given the elevated MYCN expression and cell cycle scores, we inferred that the malignant neuroblast population was highly proliferative and represented a more malignant undifferentiated neuroblastoma cell type." (PMID 40580553, 2025). "Interestingly, we observed that, as previously found for SLC3A2, ATP13A3 expression was significantly higher in MYCN‐amplified versus non‐MYCN amplified neuroblastoma tumors." (PMID 39981745, 2025). "Moreover, stage 4S neuroblastoma patients with MYCN amplification have better outcomes than stage 4 neuroblastoma patients with MYCN amplification." (PMID 41189817, 2025). "However, research on ferroptosis-related intervention targets in MYCN-amplified neuroblastoma remains limited at present." (PMID 40108662, 2025). "Additionally, compared with cisplatin, RTA-408 induced higher rates of both clonogenicity inhibition and apoptosis in MYCN-amplified neuroblastoma cells." (PMID 40493396, 2025). "Our results support a model in which NIPBL promotes MYCN binding at enhancers and sustains its repressive influence on neuronal differentiation programs, thereby reinforcing the MYCN-driven oncogenic transcriptional network that maintains the neuroblastoma phenotype." (PMID 40867243, 2025). "Their findings demonstrated that inhibiting the SELENOP/LRP8 axis represents a novel and selective strategy to trigger ferroptosis, thereby limiting the growth of highly aggressive and treatment-resistant MYCN-amplified neuroblastoma cells, confirming LRP8 as a promising therapeutic target." (PMID 40108662, 2025). "Therefore, we propose that the newly established prognostic model can be utilized to predict the prognosis of MYCN-amplified neuroblastoma patients." (PMID 40108662, 2025). "In conclusion, this study provides compelling evidence that MYCN amplification extends beyond tumor growth to influence immune evasion pathways and glycosylation processes in neuroblastoma, potentially shaping the immune landscape in ways that limit immune engagement." (PMID 39860532, 2025). "We next evaluated whether MYCN also drives polyamine uptake, as has previously been suggested for pancreatic adenocarcinoma, by utilizing Tet‐21/N neuroblastoma cells with doxycycline‐inducible MYCN silencing." (PMID 39981745, 2025). "We next investigated whether targeting KLHL37 could inhibit the progression of MYCN-amplified neuroblastoma." (PMID 40493396, 2025). "In this study, we hypothesized that combining G6PD inhibition with 5-ALA-mediated PDT would overwhelm GSH defenses and amplify the activity of ROS, resulting in the induction of enhanced cytotoxicity against MYCN-amplified neuroblastoma cells." (PMID 41291487, 2025).
neuroblastoma (continued). "Investments in research to explore genetic and molecular underpinnings of neuroblastoma, such as MYCN amplification, could inform the development of more effective, personalized therapies." (PMID 40963964, 2025). "Taken together, our findings suggest that KLHL37 might play an important role in the malignant progression of neuroblastoma, especially in patients with MYCN-amplified disease." (PMID 40493396, 2025). "However, the complex nature of the challenging MYCN protein underscores the urgent need for additional targets and therapies to tackle neuroblastoma and medulloblastoma." (PMID 40701975, 2025). "However, in MYCN-amplified neuroblastoma, the H3K4me3 mark persists, sustaining MYCN expression and promoting tumorigenesis." (PMID 40365336, 2025). "The finding of these heterozygous mutations in two patients with MYCN non-amplified neuroblastoma deserves further investigation." (PMID 40286729, 2025). "A 4-year-old boy was diagnosed with INSS high-risk stage 4, MYCN non-amplified neuroblastoma originating from the adrenal medulla, with bone, bone marrow, and lymph node metastasis." (PMID 40286729, 2025). "Given that MYCN is a known regulator of MIR17HG in neuroblastoma and medulloblastoma, we sought to determine whether MYCN is necessary for the miR-17–92 expression in these FP-RMS cells." (PMID 41473312, 2025). "MYCN was later described as an important regulator of ODC1 in neuroblastoma." (PMID 40004600, 2025). "Approximately 20% of NBs exhibit MYCN amplification (MYCN-amplified neuroblastoma, MNA-NB)." (PMID 41244073, 2025). "THZ1, a covalent CDK7 inhibitor, effectively downregulated MYCN expression, resulting in significant tumor regression in a high-risk neuroblastoma mouse model without inducing systemic toxicity or off-target effects." (PMID 40365336, 2025). "Targeting KLHL37 inhibits the progression of MYCN-amplified neuroblastoma." (PMID 40493396, 2025). "Similar to the MYCN status, DNA ploidy is a strong predictor of neuroblastoma prognosis." (PMID 38891878, 2024). "Recently, Westermann and colleagues reported 4 subgroups in neuroblastoma, including MYCN-amplified (MYCN), MYCN non-amplified high-risk (MNA-HR), MYCN non-amplified low-risk (MNA-LR) and mesenchymal (MES)." (PMID 38553589, 2024). "We discovered that AF1q is universally expressed in neuroblastoma tumors regardless of risk classification, as well as in MYCN amplified and MYCN non-amplified neuroblastoma cell lines." (PMID 38413795, 2024). "MYCN amplification is detected in 20%–30% of neuroblastoma patients." (PMID 39049899, 2024). "For example, both CSE and CBS protect MYCN-amplified neuroblastoma cells against ferroptosis." (PMID 38908072, 2024). "Lastly, while Protocol #4 may be optimal to MYCN-driven neuroblastoma, a non-MYCN-driven neuroblastoma may be better represented by a different protocol and require optimization." (PMID 39367051, 2024). "Together these findings suggest that MYCN, SNRPD3, and PRMT5 proteins may cooperatively complex to enhance SNRPD3 methylation and spliceosome assembly in MYCN-driven neuroblastoma." (PMID 38049564, 2024). "Gain-of-function in ALK could drive the neuroblastoma but requires cooperation from MYCN amplification." (PMID 38391759, 2024). "To test whether DDX1 expression was sufficient to induce mTORC1 pathway activation, we analyzed mTORC1 activity by RNA sequencing and immunoblot analyses of MYCN-amplified neuroblastoma cells after ectopic DDX1 expression." (PMID 38197697, 2024).
neuroblastoma (continued). "Together, these results raise the hypothesis that older patients with ALK-driven neuroblastoma may respond to lorlatinib as monotherapy, whereas young children harboring an MYCN amplification may benefit more from a combination regimen." (PMID 39177282, 2024). "MYCN oncogene amplification is frequently observed in aggressive childhood neuroblastoma." (PMID 38992040, 2024). "We further determined that intrinsic disorder assessments could be used for OS stratification for a second, immunologically cold cancer: MYCN amplified neuroblastoma." (PMID 39519243, 2024). "LRP8 is a selenoprotein P receptor that is important for protecting MYCN-amplified neuroblastoma." (PMID 38725484, 2024). "On the basis of our previous data showing that simultaneous KAT2A/KAT2B loss reduced neuroblastoma viability, we hypothesized that the KAT2A/KAT2B PROTAC, GSK-699, may be a pharmacologic intervention for MYCN-amplified neuroblastoma." (PMID 38820154, 2024). "In conclusion, a complex interplay of genetic changes, such as MYCN amplification, segmental chromosomal modifications, gene expression profiles, ALK mutations, and other genomic variants, contributes to the complex pathogenesis of neuroblastoma." (PMID 39612452, 2024). "Notably, MYCN was enriched at the TERT promoter in MYCN-amplified neuroblastoma cells (SKNBE2, NB5)." (PMID 38837897, 2024). "While genetic mouse models for some childhood cancers (e.g., MYCN-driven neuroblastoma) have been used to test agents that require an adaptive immune response, further research is required to develop robust panels of models across a diverse range of tumor types." (PMID 39510293, 2024). "Similarly, N-Myc has been shown to drive an increased expression of ASCT2 in MYCN-amplified neuroblastoma cells, along with activating transcription factor 4 (ATF4)." (PMID 38399253, 2024). "To confirm that this complex level dependency is enriched in MYCN-amplified neuroblastoma, we generated a metagene signature of all SAGA complex members and used ssGSEA (single-sample GSEA) to generate a dependency score for the SAGA complex for each solid tumor cell line in the DepMap dataset." (PMID 38820154, 2024). "We previously showed that neuroblastoma relies on MYCN-induced glutaminolysis for survival." (PMID 38488852, 2024). "IGF2BP1 upregulation in neuroblastoma was associated with lower overall survival and positively correlated with MYCN mRNA, even in patients with MYCN-non-amplified tumors." (PMID 38730633, 2024). "We analyzed the expression of endothelial markers (EGFL7, FLT1, PTPRB33), mesenchymal cells (COL1A2, COL1A1, PDGFRB34,35) and immune markers (ITGAM, CD247, PTPRC36–38) in MYCN-amplified neuroblastoma patient samples (with at least 90% tumor purity) and tumors from Protocol #4." (PMID 39367051, 2024). "Interestingly, hnRNPA1 was previously demonstrated to be a MYCN target gene mediating AS in neuroblastoma, and a comparison of our DSGs with DSGs reported in RNAseq of hnRNPA1/PTBP1 knockdowns demonstrated a significant overlap." (PMID 39313128, 2024). "Therefore, the MYCN gene can be amplified with the help of eccDNA, thereby increasing the expression of this gene in neuroblastoma cells, thereby promoting the tumor progression." (PMID 38662139, 2024). "We have found that AhR transcriptional activity correlates with poor patient prognosis, positively regulates MycN, and represses differentiation of MYCN-amplified neuroblastoma cells by altering chromatin accessibility and modulating the retinoic acid receptor pathway." (PMID 38807762, 2024).
neuroblastoma (continued). "In addition to MYCN gene amplification, cytogenetic abnormalities are also a marker of an unfavorable prognosis in patients diagnosed with neuroblastoma." (PMID 39049899, 2024). "The histone-methylating polycomb repressive complex 2 (PRC2) is an additional critical mediator of gene expression in MYCN-amplified neuroblastoma and inhibition of one of the complex members, enhancer of zeste homolog 2 (EZH2), has antitumor activity in some murine models." (PMID 38820154, 2024). "To investigate whether targeting SNRPD3 methylation is an effective therapeutic strategy in MYCN-amplified neuroblastoma we assessed the effects of the PRMT5 inhibitor, JNJ-64619178 in vitro." (PMID 38049564, 2024). "In bioinformatic studies of neuroblastoma, MYCN gene amplification and the ensuing dysregulation of N-MYC function have been linked to a colder tumor phenotype, lending further support to the notion that N-MYC activity may impair antitumor immunity." (PMID 38748789, 2024). "From a murine study with a transgenic mouse expressing MYCN targeted to the neural crest (TH-MYCN mice), the mouse develops neuroblastoma that begins with hyperplastic lesions in paravertebral ganglia within the first weeks after birth, escaping from the normal physiological process of cell death." (PMID 38884091, 2024). "Moreover, it is known that MYCN-amplified neuroblastoma tumours have a distinct alternative splicing pattern and exhibit greater differential splicing." (PMID 38049564, 2024). "The oncoprotein MYCN drives oncogenesis in neuroblastoma by activating the expression of genes involved in ribosome biogenesis and protein synthesis, while repressing neuronal differentiation genes, but the underlying mechanisms remain unknown." (PMID 38547242, 2024). "Taken together these results indicate that SNRPD3 may have a functional relationship with MYCN and has an important role in neuroblastoma tumorigenesis." (PMID 38049564, 2024). "Indeed, similar to that in developing sympathetic ganglion cells, the TERT promoter in MYCN-amplified neuroblastoma cells shows active chromatin marks and DNA methylation of the TERT gene body." (PMID 38837897, 2024). "We hypothesise that a similar mechanism is utilised in neuroblastoma to maintain splicing fidelity, where MYCN increases the expression of PRMT5, SNRPD3, and SNRPD3 methylation." (PMID 38049564, 2024). "A complete characterization of the specific complexes that control the epigenetic landscape in MYCN-amplified neuroblastoma is critical not only for understanding the biology of this disease but also for finding new potential avenues for therapeutic development." (PMID 38820154, 2024). "Together, these data suggest that therapeutic targeting of the SAGA complex via degradation of KAT2A and KAT2B may be a therapeutic strategy for MYCN-amplified neuroblastoma." (PMID 38820154, 2024). "In addition, in the transgenic MYCN mouse model of neuroblastoma, the chromosomal locus syntenic to human 17q is partially amplified, indicating that chromosome 17q is needed for MYC-mediated tumorigenesis." (PMID 38488852, 2024). "The lncRNA PVT-1 is also part of the MYCN transcriptional network in the context of neuroblastoma." (PMID 38891878, 2024).